IL7 (interleukin 7)
Diseases named in the same sentence as IL7 in open-access papers (continued):
Sharing a sentence is not in itself a finding about the gene and the disease.
lymphopenia (continued). "TCR-nonspecific signals include cytokines such as the cytokine interleukin-7(IL7), which is necessary for the survival of nave T cells.Lymphopenia-induced proliferation of memory cells requires IL7 or IL15." (PMID 19521511, 2009). "As anticipated, this period of relative CD4 lymphopenia was accompanied by an elevation in IL-7 and IL-15 plasma levels (compared to baseline pre-infusion levels)." (PMID 19270751, 2009). "IL-7 produced in response to lymphopenia stimulates proliferation of both naïve and memory human T-cells, but also has a direct stimulating effect on thymic activity." (PMID 15642146, 2005). "It was therefore possible that a similar deficit in IL-7 was a critical factor in the suboptimal response to lymphopenia in RA patients." (PMID 15642146, 2005). "We have also demonstrated low levels of lymphopenia-induced circulating IL-7 in RA patients, and low basal IL-7 production from stromal cells originating from the bone marrow." (PMID 15642146, 2005). "IL-7 is produced in response to lymphopenia and stimulates proliferation of both naïve and memory human T-cells." (PMID 15642146, 2005). "The threshold pattern resembles findings showing that IL‐7 primarily benefits patients with profound lymphopenia, consistent with the concept that immune‐directed interventions may demonstrate differential efficacy at specific immune cell concentrations." (PMID 41492360, 2026). "A phase II clinical study involving 27 patients who experienced septic shock and severe lymphopenia demonstrated that IL-7 therapy led to considerable increases in the counts of CD4+ and CD8+ T lymphocytes without producing an excessive inflammatory response or increased organ dysfunction." (PMID 40153575, 2025). "Additionally, RS appeared to mitigate postoperative lymphocytopenia, potentially via IL-7 activity, and favored a Th1-dominant response while preserving immunocompetence, as indicated by upregulation of HLA-DR expression on postoperative day three." (PMID 41155334, 2025). "Therapies to improve lymphopenia may also be of interest for patients with GBM such as adoptive cell therapies or IL-7 treatments to boost T cell counts." (PMID 41282244, 2025). "This study aimed to investigate the dynamics of endogenous plasma levels of IL-7 during sepsis and septic shock, correlating its levels with lymphopenia and various lymphocyte subtypes, including CD4+ and CD8+ T cells, B cells, and natural killer T cells (NKT), in both survivors and non-survivors." (PMID 40005375, 2025). "The increased IL-7 signaling may be a response to the lymphopenia to support the survival of existing T cells in VL." (PMID 38408097, 2024). "Importantly, in the presence of lymphopenia, the survival and proliferation of naïve T cells are reliant on IL-7, as indicated by the inability of these cells to survive in hosts lacking IL-7." (PMID 38675377, 2024). "NT-I7, a longer-acting IL-7 Fc, was tested for its ability to prevent systemic lymphopenia and improve survival in a GBM mouse model, and it was demonstrated that in a mouse model of glioma in situ, NT-I7 increased central and effector memory CD8+ T cells in both lymphoid organs and tumours." (PMID 38675377, 2024). "Furthermore, in the presence of lymphopenia, IL-7 not only leads to the IL-7-dependent activation of STAT1 and STAT5 but also enhances the T cell response to IFN by regulating STAT1 protein expression levels." (PMID 38675377, 2024). "Significantly increased IL-7 levels in PE may reflect a compensatory response to lymphopenia through enhanced T cell proliferation." (PMID 39737183, 2024). "One corollary to our study would be an alternative use of IL7 as a treatment for lymphopenia, whether it be in the setting of radiation induced lymphopenia or other general leukopenia disorders." (PMID 38554147, 2024).
lymphopenia (continued). "Considering that lymphopenia is usually a result of concurrent chemoradiation, IL‐7 administered during or after concurrent chemoradiation might be an alternative to prevent or reverse lymphopenia." (PMID 36583472, 2023). "Our studies also found that persistent antigen stimulation caused lower IL-7 levels in serum and decreased the proportion of lymphoid progenitors, while rAAV2-IL-7 treatment significantly promoted the elevation of BM lymphoid progenitors and partially reverse lymphopenia." (PMID 36743311, 2023). "In some cases, reports showed that IL-7 could be safely used in patients with severe COVID-19 and absolute lymphocytopenia and can benefit patients." (PMID 38114466, 2023). "The effect of IL-7 to reverse sepsis-induced lymphopenia occurs via two independent mechanisms." (PMID 36906875, 2023). "In the periphery, IL-7 has a key role in T-cell homeostatic proliferation and its production is tightly regulated, as the levels of IL-7 in the peripheral blood increase during lymphopenia remaining high until T-cell pool returns to steady state conditions." (PMID 35734178, 2022). "Plasma levels of the homeostatic cytokine IL-7 are typically elevated during lymphopenia and may contribute to cell cycling and proliferation." (PMID 35967371, 2022). "Furthermore, IL-7 has been shown to regulate CD4 T cell proliferation in conditions of lymphopenia indirectly though DCs22." (PMID 34997007, 2022). "Various strategies could be applied to treat SARS-CoV-2 infected patients, in particular IL-7, which could promote T-cell proliferation, prevent T-cell death, and help reverse lymphopenia in severe patients." (PMID 35330349, 2022). "Most recently, IL-7 administration has been used in a murine model of age-related lymphopenia." (PMID 35734178, 2022). "Nevertheless, oxidative stress may lead to lymphopenia through the diminished responsiveness of T-cells to IL-7, as observed in the human immunodeficiency virus." (PMID 36499671, 2022). "IL‐7 is a pleiotropic cytokine that provides an indispensable homeostatic survival signal to Tn cells and that drives Tn and other T‐cell subsets into homeostatic proliferation under the conditions of lymphopenia." (PMID 35289071, 2022). "Various cell types produce IL-7 and IL-15, primarily in lymphoid tissues under lymphopenia." (PMID 33809452, 2021). "Because it is generally assumed that during lymphopenia the availability of growth and survival factors increases, which has in particular been shown for IL-7 plasma levels, we also determined plasma levels of IL-7 and IL-15 between 12 and 24 months post-autoHSCT." (PMID 33538246, 2021). "Second, lymphopenia triggers immune system regeneration phase, marked by lymphocyte proliferation homeostasis motored by interleukin (IL)-7 and IL-15, so the immune response could return to normal state in a period after chemotherapy." (PMID 34837913, 2021). "Other immune modulating strategies that can be expected to modulate microbicidal responses include recombinant IL-7, which corrects lymphopenia and will enhance IFN-γ, and intravenous immunoglobulin (IVIG), which in addition to immunomodulation enhances pathogen clearance through phagocytosis." (PMID 32582139, 2020). "In conclusion, we strongly believe that IL-7 is worth trying in next trials when patients could be stratified based on marked lymphopenia." (PMID 32728202, 2020). "Although the correlation between radiation exposure and IL7 production is tenuous, we propose that increased IL7 levels in vivo may contribute to relief against radiation induced lymphopenia." (PMID 30978983, 2019). "Lymphopenia-induced homeostatic proliferation depends on IL-7 signaling." (PMID 30886618, 2019). "Despite the fact that MAPC cells did not impair ATG-driven T cell HP, it was hypothesized that MAPC cells would suppress IFN-γ production by T cells in this lymphopenia-driven model in a similar manner to the IL-7 model." (PMID 29740426, 2018).
lymphopenia (continued). "Studies in conditions with elevated IL-7 levels, due to lymphopenia or pharmacologic administration of IL-7, indicate that IL-7 in high concentrations may enhance the proliferative responses even to weak self-antigens." (PMID 29456530, 2018). "Disruption of the IL-7 axis leads to severe lymphopenia, and administration of IL-7 in HIV seropositive people and patients suffering from other types of lymphopenia, results in rapid replenishment of the T cell pool, promote T cell expansion and normalization of lymphocyte functions." (PMID 30157233, 2018). "While this study demonstrates that MAPC cells suppress proliferation and activation of T cells in response to IL-7 and lymphopenia over a short period of time, the effect of MAPC cells on long-term immune reconstitution and how it would impact graft survival remains to be shown." (PMID 29740426, 2018). "Similar to lymphopenia, IL-7 has also been effective in the prevention of infections." (PMID 29904108, 2018). "Given the long-held perception that lymphopenia in mice and humans is associated with increased IL-7 in circulation, our data showing no overt increase in IL-7 availability after lymphodepleting chemotherapy is somewhat surprising." (PMID 28939858, 2017). "Based on these findings, new clinical trials studying the administration of recombinant IL-7 are currently being evaluated in an attempt to reverse lymphopenia and sepsis-induced immunosuppression in sepsis patients (ClinicalTrials.gov identifier: NCT02640807 and NCT02797431)." (PMID 28287491, 2017). "It is also possible that the level of IL-7 is correlated with the degree of lymphopenia." (PMID 28939858, 2017). "In lymphopenia, lymphatic endothelial cells produce IL-7 that increases plasma levels." (PMID 28579989, 2017). "Therefore, the requirement for ongoing thymopoiesis questions the suggested benefit of IL-7 therapy in the recovery of lymphopenia in thymectomized individuals." (PMID 28154568, 2017). "Here, we transferred in vitro-activated transgenic OT-I CD8+ effector T-cells into irradiation (600 rads)-induced lymphopenic C57BL/6, IL-7 knockout (KO) and IL-15 KO mice, and investigated the survival and memory formation of transferred T-cells in lymphopenia." (PMID 27158441, 2016). "It is well-known that irradiation removes the sinks for homeostasis cytokines such as IL-7 and IL-15 leading to IL-7 and IL-15 increase in lymphopenia, and induces radiation-sensitive hematopoietic cell apoptosis, leading to releasing its IL-15Rα and subsequent formation of IL-15/IL-15Rα complexes." (PMID 27158441, 2016). "We hypothesize that it is the reduction in Il-7 expression which initiates lymphopenia by restricting lineage commitment, indicating that changes to the BM niche are responsible for the hematopoietic disruption observed in these studies." (PMID 24595332, 2014). "Circulating IL-7 levels increase during periods of lymphopenia to maintain naïve T-cell homeostasis and support the thymic-independent peripheral expansion and maintenance of mature T cells because they upregulate bcl-2 protein that has antiapoptotic properties." (PMID 24971338, 2014). "In addition, CD4+ T cells that survive cytoreductive chemotherapy and harbor HIV-1 DNA are likely to proliferate in response to chemotherapy-induced lymphopenia through IL-7 mediated homoestatic proliferation." (PMID 24638072, 2014). "In patients with HIV infection, the relatively weak association observed between IL-7 and levels of t-STAT1 suggests that lymphopenia in combination with other factors potentially driven by ongoing viral replication may play a role." (PMID 24603698, 2014). "In addition, more recent evidence suggest that lymphopenia also triggers an increased production of IL-7 by stromal cells in the thymus and possibly the bone marrow." (PMID 23383227, 2013).
lymphopenia (continued). "Moreover, IL-7 treatment counteracted IFN-α therapy-induced lymphopenia and stimulated SIV-specific cytotoxic T lymphocyte responses in SIV-infected rhesus macaques." (PMID 22958464, 2012). "Ongoing phase 3 trials should indicate whether IL-7 has a role in correcting lymphopenia in patients who fail to recover CD4 T cell counts under HAART (or in purging the viral reservoir )." (PMID 22958464, 2012). "It remains to be seen whether systemic use of other common γ chain cytokines, such as IL-7 or IL-21, could be useful for particular indications (e.g. to counteract lymphopenia)." (PMID 22958464, 2012). "Furthermore, homeostatic cytokines such as IL-7 and IL-15, that are prevalent during lymphopenia, have been shown to be able to substitute for IL-2 signaling in activated effector cells." (PMID 22383993, 2012). "Several investigators observed increased serum levels of IL-7 in HIV-1-infected patients characterized by severe CD4+ lymphopenia, and showed direct correlation between IL-7 serum concentration and viral load, loss of CD4+ T cells, and alteration of B cell subsets." (PMID 22474482, 2012). "In addition to the documented ability of IL-7 to induce reactivation of latent HIV-1 in resting cells from patients, recombinant IL-7 (rIL-7) has shown efficacy in combating lymphopenia when administered to HIV-1 patients." (PMID 21998586, 2011). "A close link between CD4+ T cell depletion and increased blood IL-7 levels has been demonstrated in HIV-1 infection and in other, non-HIV related conditions of lymphopenia possibly reflecting the decreased IL-7 consumption associated with the loss of T cells." (PMID 22194871, 2011). "Although the potential effects of the lymphopenia induced higher IL-7 levels remain speculative, animal models indicated that the modulation of IL-7 levels has a strong impact on T cell homeostasis." (PMID 22194871, 2011). "It is well known that lymphopenia is invariably associated with homeostatic expansion of the remaining T cells in the periphery, in response to endogenous MHC ligands and IL-7, but also with immune reactivity, both to self- and foreign antigens not normally apparent in T cell–replete hosts." (PMID 18974880, 2008). "Therefore, the results are in favor of an increased IL-7R engagement, and we can suggest that STING GOF T cells are more activated by IL-7 because they will encounter an abnormal amount of IL-7 per T cell, compared to a physiological situation, as described in lymphopenia-induced proliferation." (PMID 40804163, 2025). "Further, in the expanding era of immunotherapy, it remains to be tested whether limiting or reversing lymphopenia (e.g., lymphocyte re-infusion, lymphocyte expansion with IL-7) may help uncover the yet to be realized potential of immunotherapy for the treatment of GBM." (PMID 38481255, 2024). "Furthermore, despite important lymphopenia, NSG mice may have low levels of IL-7 due to their mutations hampering the function of the key organs producing IL-7 (LNs, thymus, and BM)." (PMID 39543777, 2024). "IL-7 could reverse impaired hematopoiesis and lymphopenia by decreasing IFN-γ and TNF-α levels." (PMID 36743311, 2023). "IL-7 is known to drive the homeostatic expansion of human naive CD4+ T cells during early life lymphopenia, which led us to examine whether differences in IL-7 receptor (IL-7R) signaling might contribute to the preferential expansion of prenatal naive PLZF+CD4+ T cells." (PMID 37856221, 2023). "Interleukin (IL)-7 is broadly active on T-cell populations, and modified versions have been clinically evaluated for a variety of therapeutic applications, including cancer, lymphopenia, and infectious diseases; and found to be relatively well-tolerated and biologically active." (PMID 37874823, 2023).
lymphopenia (continued). "Increased IL-7 production in response to lymphopenia suggests the presence of functioning thymic epithelial cells; failure to mount IL-7 production as observed in patients 5 and 6 suggests thymic dysfunction which may reflect ongoing active thymic aGVHD and/or irreparable thymic damage." (PMID 33651234, 2021). "Moreover, increased IL-2 and IL-7, which are the cytokines responsible for the expansion and differentiation of T cell subsets, may attempt to reverse lymphopenia and T cell exhaustion." (PMID 33365277, 2020). "Lymphopenia may cause high IL-7 plasma levels and few reports indicated a role of lymphopenia in tuberculosis, but this has not been verified by others." (PMID 28582466, 2017). "On the other hand, given the direct role that IL-7 signaling plays in augmenting reactivity to self-antigens during lymphopenia because of excessive levels of IL-7, manipulation of BMP signaling might be considered for prevention of autoimmune diseases in lymphopenic individuals." (PMID 26110906, 2015). "In addition, IL-7 is important for T cell homeostasis and lymphopenia-driven proliferation." (PMID 25955647, 2015). "As lymphopenia is typically characterized by increased levels of IL-7 and having shown that IL-7 availability increases Treg reactivity to IL-2, we speculated that IL-7 could affect IL-2 induced Treg expansion." (PMID 25485946, 2014). "Therefore, lymphopenia and increased availability of IL-7 generates a complex environment." (PMID 24603698, 2014). "Similarly, the overabundance of IL-7 under lymphopenic conditions contributes to the activation of adoptively transferred, naïve T lymphocytes, which undergo lymphopenia-induced proliferation (LIP), convert into effector/memory T cells and cause inflammation in the large intestine." (PMID 22384106, 2012). "The causes of this Tnaive lymphopenia are not certain but may involve reduced thymic output, lack of IL-7 and increased activation-induced apoptosis in ESRD patients." (PMID 21214947, 2011). "Patients with lymphopenia might merit lymphocyte-sparing strategies—such as avoiding unnecessary corticosteroids or using radiotherapy plans that minimize lymphocyte dose—and could benefit from adjunctive measures including nutritional support or exploratory IL-7–based interventions." (PMID 41225450, 2025). "We searched PubMed, Embase, and Web of Science from inception to April 24, 2025, using terms such as Interleukin-7, CD127, CYT107, interleukin-7 receptor, sepsis, septic shock, and lymphopenia." (PMID 41158471, 2025). "When T cell homeostasis is dysregulated and lymphopenia occurs (e.g., following myeloablative chemotherapy or CD4+ T cell depletion following HIV infection), IL-7 consumption declines and serum IL-7 levels increase." (PMID 31507594, 2019). "Taken together, we demonstrated different perioperative dynamics of interleukin-7, which may contribute to favourable outcomes following robotic colorectal surgery including lower incidence of surgical site infections, milder surgery-induced lymphopenia, and beneficial interferon-γ dynamics." (PMID 29904108, 2018). "During chronic HIV/simian immunodeficiency virus (SIV) infection, plasma IL-7 levels increase with the establishment of lymphopenia, patients with lower than 200 CD4+ cells/mL presenting with the highest IL-7 plasma levels." (PMID 28579989, 2017). "Dissecting the relative contribution of lymphopenia to the signaling pathways in naïve T cells where GIMAP5 appears to be required for both TCR and IL-7 mediate signaling, will be a challenge." (PMID 27023180, 2016). "Since IL-7 in vitro was able to upregulate t-STAT1, we next analyzed its contribution in the setting of lymphopenia." (PMID 24603698, 2014). "We next evaluated the contributions of in vivo lymphopenia (CD4 T cell counts) and serum levels of IL-7 to t-STAT1 expression and activation (p-STAT1) in patients with chronic HIV infection." (PMID 24603698, 2014).